TRAF6 (TNF receptor associated factor 6)
Diseases named in the same sentence as TRAF6 in open-access papers (continued):
Sharing a sentence is not in itself a finding about the gene and the disease.
cardiac hypertrophy (continued). "In addition, several E3 ubiquitin ligases including MuRF1, Atrogin‐1, Carboxyl terminus of HSP70‐interacting protein (CHIP) and Tumour Necrosis Factor Receptor‐Related Factor 6 (TRAF6), have been reported to participate in the pathological cardiac hypertrophy." (PMID 40753540, 2025). "Furthermore, heart‐specific overexpression of TRAF6 aggravated myocardial hypertrophy in response to pressure overload or stimulation with angiotensin II." (PMID 30950211, 2019). "Overall, TRAF6 plays a critical role in the induction of cardiac hypertrophy and may prove to be a potential therapeutic target." (PMID 30186311, 2018). "On similar lines, the in vitro studies involving NCRMs infected with adenovirus harboring TRAF6 cDNA (AdTraf6) showed notably increased cardiac hypertrophy and increased ANP and β-MHC levels after 48 h on similar induction with Ang II or PE as compared to controls." (PMID 30186311, 2018). "The Tak1-dependent effect of Traf6 on cardiac hypertrophy in vitro prompted us to evaluate whether the activation of Tak1 is responsible for Traf6-mediated cardiac hypertrophy in vivo." (PMID 27249171, 2016). "To evaluate whether ROS production contributes to increased TRAF6 expression during cardiac hypertrophy, we subjected NRCMs to H2O2 stimulus and found that TRAF6 protein expression was gradually enhanced from 6 to 48 h of H2O2 challenge." (PMID 27249171, 2016). "To explore the potential involvement of TRAF6 in the development of pathological cardiac hypertrophy, we first investigated whether TRAF6 expression was altered in failing human hearts and in a mouse model of cardiac hypertrophy." (PMID 27249171, 2016). "Based on the fact that ROS production induces a dramatic increase in Traf6 expression that significantly promotes cardiac hypertrophy development, we next asked whether ROS blockage could neutralize the pro-hypertrophic effect of Traf6." (PMID 27249171, 2016). "The dramatic increase in Traf6 induced by ROS production upon pro-hypertrophic administration prompted us to investigate whether the increased Traf6 contributes to cardiac hypertrophy." (PMID 27249171, 2016). "However, the role of TRAF6 in TGFBR1 regulation of TAK1-mediated cardiac hypertrophy and PANoptosis remains unclear." (PMID 40880411, 2025). "Also, TRAF6 may contemplate as a potential therapeutic target owing to its crucial involvement in cardiac hypertrophy." (PMID 30186311, 2018). "Deleting or mutating (C70A mutant) TRAF6 ring domain (with ubiquitin ligase activity) inhibits both K63 ubiquitination of TAK1 and activation of p38 and JNK signaling, demonstrating the importance of TRAF6 E3 ligase activity in inducing pathologic cardiac hypertrophy." (PMID 30186311, 2018). "Therefore, whether the potential role of TRAF6 in autophagic activity contributes to pathological cardiac hypertrophy remains to be further elucidated." (PMID 27249171, 2016). "During recent years, several E3 enzymes, such as F-box protein atrogin-1, muscle ring finger-1, TRAF6, and CDC20 have been reported to play roles in the development of cardiac hypertrophy through different mechanisms." (PMID 33585485, 2021). "Here the authors show that ROS, generated during pathological cardiac stress, induces TRAF6 auto-ubiquitination and activation, promoting its interaction with and ubiquitination of TAK1 that contributes to development of cardiac hypertrophy." (PMID 27249171, 2016). "However, the role of TRAF6 in cardiac hypertrophy remains unknown." (PMID 27249171, 2016). "Consistently, the mRNA levels of markers related to cardiac hypertrophy and fibrosis, including Anp, Bnp, β-Mhc, collagen I, collagen III and Ctgf, were markedly elevated in the hearts of Traf6-TG mice compared with NTG controls." (PMID 27249171, 2016).
cardiac hypertrophy (continued). "In the present study, we observe elevated protein levels of TRAF6 in the hearts of patients with hypertrophic cardiomyopathy (HCM) or dilated cardiomyopathy (DCM) and in animal models of cardiac hypertrophy induced by aortic banding (AB)." (PMID 27249171, 2016). "Accordingly, we deduced that Myr alleviated cardiac hypertrophy through inhibiting TAK1 activation, which could be regulated by TRAF6 ubiquitination." (PMID 31885808, 2019). "TRAF6 is prominently expressed in myocardial tissue, and activation of TRAF6 was shown to contribute to TAK1 ubiquitination, followed by an accelerated development of cardiac hypertrophy and fibrosis in a mouse aortic banding model." (PMID 30175152, 2018). "In addition, inhibition of TAK1 binding to TRAF6 has been shown to inhibit TAK1 mediated JNK1/2 and p38 signaling and subsequently inhibiting cardiac hypertrophy both in vivo and in vitro." (PMID 30186311, 2018). "In summary, we provide the evidence that endogenous TRAF6 is an essential molecular switch for the development of pathological cardiac hypertrophy, which is dependent on TRAF6 ubiquitination, TRAF6–TAK1 interactions, and the TRAF6-induced ubiquitination of TAK1." (PMID 27249171, 2016). "In addition to the Traf6-TG mice, a cardiac-specific Traf6 deletion mouse line (Traf6-CKO) was created and subjected to AB surgery to further confirm the regulatory function of Traf6 in cardiac hypertrophy." (PMID 27249171, 2016). "In the current study, utilizing cardiac-specific genetic manipulation, we provided robust evidence suggesting that TRAF6 promotes the activation of TAK1, a MAPK kinase kinase (MAPKKK) that controls the downstream JNK1/2 and p38 MAPK cascades, during cardiac hypertrophy." (PMID 27249171, 2016). "Thus, targeting TRAF6 and/or its interaction with TAK1 may represent promising strategies for reversing pathological cardiac hypertrophy." (PMID 27249171, 2016).
glioblastoma (11 papers, 2012 to 2024). The most malignant astrocytic tumor (WHO grade IV). "Our findings illustrate that PRMT6 suppresses TRAF6 transcription via H3R2me2a to enhance the protein stability of EZH2 to facilitate glioblastoma cell invasion and migration." (PMID 39043634, 2024). "We transfected the small interfering RNA targeting TRAF6 into PRMT6-silenced glioblastoma cells to achieve re-inhibition of TRAF6, and subsequently observed an upregulation of EZH2 expression." (PMID 39043634, 2024). "Throughout our study, we identified that TRAF6 is a regulator of EZH2 stability through ubiquitination in glioblastoma cells." (PMID 39043634, 2024). "Together, these results uncover an essential role of PRMT6 in regulating TRAF6 expression by adding an activating histone methylation mark (H3R2me2a), that is, PRMT6 suppresses the transcription of TRAF6 in glioblastoma cells." (PMID 39043634, 2024). "To determine the role of TRAF6 in regulating EZH2 protein homeostasis in glioblastoma cells, we performed Co-IP experiments in U87, LN229, and HEK293T cells." (PMID 39043634, 2024). "The inverse relationship between the expressions of TRAF6 and miR-146b-5p was further validated by the glioblastoma data from TCGA database (r = −0.506, P < .0001)." (PMID 26320176, 2015). "Additionally, our further investigations revealed a notable up-regulation in the transcription of TRAF6 in PRMT6-depleted glioblastoma cells." (PMID 39043634, 2024). "Here, our data confirm that PRMT6 mediates the asymmetric dimethylation of histone H3 at arginine 2 (H3R2me2a) to inhibit the transcription of TRAF6, resulting in a significant decrease in the expression levels of TRAF6 in glioblastoma cells with PRMT6 overexpressing." (PMID 39043634, 2024). "Additionally, rescue experiments demonstrated that PRMT6 enhances glioblastoma cell invasion and migration by modulating TRAF6-mediated EZH2 expression." (PMID 39043634, 2024). "Through in vitro studies, we found that both transfected miR-146b-5p and TRAF6 siRNA significantly reduced the Ki-67 expression (P < 0.05∼0.001) and proliferation (P < 0.05∼0.001) of glioblastoma cell lines, as measured by Western blotting and CCK8 proliferation assay." (PMID 26320176, 2015). "Our in vitro results showed that both miR-146b-5p and TRAF6 siRNA could effectively decrease the Ki-67 expression and proliferation of glioblastoma cells, and miR-146b-5p also significantly promoted the apoptosis of glioblastoma cells." (PMID 26320176, 2015). "Detailed examination indicated that the highest expressions of TRAF1, TRAF2, TRAF3, TRAF5, and TRAF7 were in Cholangiocarcinoma (CHOL), while TRAF4 was most expressed in Uterine Corpus Endometrial Carcinoma (UCEC) and TRAF6 in Glioblastoma multiforme (GBM)." (PMID 38825674, 2024). "In glioblastoma and head and neck cancer, phosphorylated DCBLD2 recruits tumor necrosis factor receptor-associated protein 6 (TRAF6), which leads to the increased E3 ubiquitin ligase activity of TRAF6 and ubiquitin-mediated AKT activation, thereby enhancing EGFR-driven tumorigenesis." (PMID 33808696, 2021). "Moreover, glioblastoma patients could also be divided into two subgroups with different outcomes based on TRAF6 expression, i.e., the higher expression of TRAF6 was, the poorer prognosis of patients (DFS: P < 0.0001; OS: P < 0.0001)." (PMID 26320176, 2015). "In glioblastoma cell lines, silencing of TRAF6 could mimic the anti-tumor effect of miR-146b-5p." (PMID 26320176, 2015). "The results showed that depletion of PRMT6 increased both the mRNA and protein levels of TRAF6, while overexpression of PRMT6 suppressed the transcription of TRAF6 in glioblastoma cells." (PMID 39043634, 2024). "Further mechanistic investigations found that PRMT6 inhibits the transcription of TRAF6 by activating the histone methylation mark (H3R2me2a), and reducing the interaction between TRAF6 and EZH2 to enhance the protein stability of EZH2 in glioblastoma cells." (PMID 39043634, 2024).
glioblastoma (continued). "Our results demonstrate that TRAF6 interacts with EZH2, facilitating its ubiquitination and subsequent degradation in glioblastoma cells, in line with existing research." (PMID 39043634, 2024). "Then, western blotting revealed that inhibition of TRAF6 expression in glioblastoma cells promoted the upregulation of EZH2 protein levels, while increased expression of TRAF6 had the opposite effect." (PMID 39043634, 2024). "The protein expression of EZH2 in MG132-treated TRAF6-silenced glioblastoma cells was investigated, and western blotting results showed that EZH2 protein levels were further up-regulated compared with TRAF6-silenced glioblastoma cells." (PMID 39043634, 2024). "To further assess the effect of TRAF6 on EZH2 protein stability, we examined EZH2 abundance in TRAF6-depleted glioblastoma cells or TRAF6-overexpressed HEK293T cells treated with CHX." (PMID 39043634, 2024). "On the other hand, in ovarian cancer cells and glioblastoma cells that show persistent NF-κB activity and high levels of TRIP6, both A20 and CYLD bind to TRAF6 very weakly." (PMID 27134758, 2016). "Anand Iyer, et.al 2012 reported that miR-146a mimics can significantly reduce the mRNA expression levels of TRAF6, IRAK1 and IRAK2 protein levels in IL-1β stimulated human astrocytes and glioblastoma cell line." (PMID 25083878, 2014). "In both the glioblastoma cell line and human astrocytes transfection with miR-146a mimic, significantly reduced IRAK-1, IRAK-2 and TRAF-6 mRNA and IRAK-1 protein after stimulation with IL-1β." (PMID 23028621, 2012). "Further investigation into the 100 bp∼−2000 bp region encompassing the TRAF6 promoter in glioblastoma cells demonstrated that PRMT6 and H3R2me2a were significantly enriched at 1400 bp∼1101 bp (F5) and 2000 bp∼1701 bp (F7) upstream of the TRAF6 transcription start site." (PMID 39043634, 2024). "Furthermore, we used EPZ020411 to treat glioblastoma cells for 48 h and obtained similar results, indicating that inhibition of PRMT6 can promote the expression of TRAF6." (PMID 39043634, 2024). "The results reveal that miR-146b-5p may bind with TRAF6 3′-UTR and inhibit TRAF6 protein expression through inducing degradation of its mRNA in glioblastoma cells." (PMID 26320176, 2015). "In summary, our research illustrates that PRMT6 acts as an epigenetic regulator, suppressing TRAF6 transcription through histone arginine methylation (H3R2me2a) to inhibit the ubiquitination and degradation of EZH2, thereby promoting invasion and migration of glioblastoma cells." (PMID 39043634, 2024). "Xenograft tumor assay and HE staining results showed that the expression of PRMT6 could promote the invasion of glioblastoma cells in vivo, the immunohistochemical staining results of mouse brain tissue tumor sections also confirmed the regulatory relationship between PRMT6, TRAF6, and EZH2." (PMID 39043634, 2024).
myocardial infarction (11 papers, 2019 to 2025). Gross necrosis of the myocardium, as a result of interruption of the blood supply to the area, as in coronary thrombosis. "The expression of TRAF6 and phosphorylated IKKα/β was increased in the group of exosomes from myocardial infarction with low expression of miR-146a-5p compared with the healthy subjects." (PMID 35548775, 2022). "This study demonstrated that circ_0010729 knockdown attenuated hypoxia-induced cardiomyocyte dysfunction via miR-370-3p/TRAF6 axis, indicating a potential therapeutic target for myocardial infarction." (PMID 33250684, 2020). "TRAF6 expression and its ubiquitination are upregulated in cancer cachexia, cardiac ischemia/reperfusion injury and myocardial infarction." (PMID 31635168, 2019). "MiR-146a plays an important role in myocardial infarction pathology by targeting two toll-like receptors (Irak1 and Traf6)." (PMID 31092195, 2019). "Inhibition of the high-mobility group box-1 (HMGB1)/TLR4/TRAF6/NF-κB signaling pathway is beneficial for treatments of MI/R injury and acute myocardial infarction (AMI)." (PMID 32038243, 2019). "Dexmedetomidine decreased myocardial infarction size and cell apoptosis through miR-146a-3p targeting IRAK1 and TRAF6 via inhibition of the NF-κB pathway." (PMID 38951872, 2024). "By upregulating miR-125a-5p and inhibiting the TRAF6/IRF5 signaling pathway, macrophage polarization toward the M2 phenotype is promoted, reducing the inflammatory response after myocardial infarction, improving cardiac function and structure, and alleviating AMI." (PMID 41583440, 2025). "In myocardial infarction models, METTL3-mediated m6A modification within microglia activates the TRAF6/ECSIT signaling pathway, induces mitochondrial oxidative stress in PVN neurons, and stimulates sympathetic hyperactivity, thereby contributing to the development of post-MI ventricular arrhythmias." (PMID 41294833, 2025). "As a result of weak GMA intervention, the expression of TLR4, TRAF6, NF-κB, and TNF-α was significantly decreased, the expression of MyD88 and MCP-1 was increased, the inflammatory response was blunted, the area of myocardial infarction was reduced, and cardiac function was improved." (PMID 38197985, 2024).
Alzheimer disease (10 papers, 2013 to 2025). A progressive, neurodegenerative disease characterized by loss of function and death of nerve cells in several areas of the brain leading to loss of cognitive function such as memory and language. "Gene expression analysis of publicly available datasets representing human AML samples revealed that reduced expression of TRAF6 is associated with mitochondrial function-related and disorder-related gene sets, such as Huntington’s, Parkinson’s, and Alzheimer’s diseases." (PMID 38609495, 2024). "Experimentally proven targets of miR-146a include complement factor H (CFH), interleukin-1 receptor-associated kinase-1 (IRAK1) and TNF receptor-associated factor 6 (TRAF6), all associated with innate immunity and inflammatory pathways which are dysregulated in Alzheimer's disease." (PMID 24133413, 2013). "It has been found that blocking TRAF6 limits the inflammatory response-mediated by intracranial hemorrhage, Alzheimer’s disease, and Salmonella typhimurium infection." (PMID 34489703, 2021). "Likewise, miRNA-146 administered from MSC-EVs has been found to inhibit microglial neuroinflammation by inhibiting TRAF6 and IL-1 receptor-related kinase 1 in microglia in patients with Alzheimer’s disease." (PMID 38741170, 2024). "Targeting the c-Src–Traf6 pathway may hold potential for the treatment of Alzheimer's disease and other tauopathies." (PMID 37977223, 2023). "Furthermore, TRAF6 is proposed to play a role in Alzheimer’s disease (AD) and neuroinflammation." (PMID 34680901, 2021). "Moreover, phosphorylation of Traf6 is highly correlated with AEP activation, Tau368 and pathological Tau (AT8) in Alzheimer's disease brain." (PMID 37977223, 2023). "In Alzheimer’s disease research, studies have shown that gastrodin reduces neuroinflammatory responses and microglial overactivation in the central nervous system of AD models by regulating the TLR4/TRAF6/NF-κB pathway, thereby contributing to its therapeutic effects against AD." (PMID 41001345, 2025).
non-small cell lung carcinoma (10 papers, 2013 to 2025). A group of at least three distinct histological types of lung cancer, including non-small cell squamous cell carcinoma, adenocarcinoma, and large cell carcinoma. "Furthermore, exosomes released by non-small cell lung cancer cells inhibit the expression of TNF receptor-associated factor 6 (TRAF6) and interleukin-1 receptor-associated kinase (IRAK1) in M0 macrophages, impairing M1 polarization and diminishing their ability to eliminate tumor cells." (PMID 38655063, 2024). "Recently, suppression of TRAF6 expression through overexpression of miR-146a resulted in deregulation of tumor cell proliferation in non-small cell lung cancer." (PMID 33142239, 2020). "In non-small cell lung cancer, miR-146a-5p overexpression was found to promote proliferation and migration via the direct suppression of TRAF6, and in oral squamous cell carcinoma, greater miRNA-146a expression was observed to enhance cell migration and invasion." (PMID 40277937, 2025). "Non-small cell lung cancer cells (NSCLC) secrete exosomal miR-146a, which inhibits TRAF-6 and IRAK-1 expression in TAMs." (PMID 38523627, 2024). "Although TRAF6 is frequently amplified and acts as an oncogene in non-small cell lung carcinoma, the activation of TRAF6 is not crucial to NFκB activation in HNSCC cells." (PMID 24302991, 2013). "Interaction of LIMD1 with TRAF6 enhances the ability of TRAF6 to activate AP1 and negatively regulates the canonical Wnt receptor signaling pathway in osteoblasts, and interaction with p65 negatively regulates NFκB activity in human non-small cell lung cancer cells." (PMID 29464072, 2018).